TMEM129 (transmembrane protein 129, E3 ubiquitin ligase)
Description:
E3 ubiquitin-protein ligase involved in ER-associated protein degradation, preferentially associates with the E2 enzyme UBE2J2. Exploited by viral US11 proteins to mediate HLA class I proteins degradation.
Synonyms: D4S2561E
Tractability: Antibody: UniProt predicts a signal peptide or a membrane-spanning region. PROTAC: ubiquitination databases record sites on it.
Gene: Protein-coding gene on chromosome 4 (1,715,951 to 1,721,358, reverse strand). Ensembl gene ENSG00000168936.
Subcellular location: Endoplasmic reticulum membrane
Pathways (Reactome):
Metabolism of proteins: E3 ubiquitin ligases ubiquitinate target proteins
Gene Ontology:
Molecular function: ubiquitin protein ligase activity
Biological process: ERAD pathway; protein polyubiquitination; retrograde protein transport, ER to cytosol; ubiquitin-dependent protein catabolic process; protein ubiquitination
Cellular component: endoplasmic reticulum; endoplasmic reticulum membrane; membrane
Genetic constraint (gnomAD): Loss-of-function variants: 35 observed, 25.33 expected, observed/expected ratio (o/e) 1.38, 90% interval 1.05 to 1.8. The synonymous counts are far from expectation, so gnomAD's model fits this gene poorly and the ratio says little. Missense variants: 504 observed, 423.56 expected, observed/expected ratio (o/e) 1.19, 90% interval 1.11 to 1.28. Synonymous variants: 239 observed, 182.43 expected, observed/expected ratio (o/e) 1.31, 90% interval 1.18 to 1.46.
Homologues: Orthologues: chimpanzee TMEM129 (100% identical), macaque TMEM129 (95% identical), dog TMEM129 (91% identical), guinea pig TMEM129 (91% identical), pig TMEM129 (91% identical), rat Tmem129 (90% identical), mouse Tmem129 (89% identical), tropical clawed frog tmem129 (75% identical), zebrafish tmem129 (65% identical), Drosophila melanogaster CG14646 (32% identical), Caenorhabditis elegans C34F6.7 (25% identical).
Diseases named in the same sentence as TMEM129 in open-access papers:
TMEM129 is named in the same sentence as 9 diseases in open-access papers, as found by Europe PMC text mining. Sharing a sentence is not in itself a finding about the gene and the disease. The quoted sentences say what the papers report.
osteoarthritis (2 papers, 2022 to 2024). A noninflammatory degenerative joint disease occurring chiefly in older persons, characterized by degeneration of the articular cartilage, hypertrophy of bone at the margins and changes in the synovial membrane. "TMEM129 encodes an enzyme involved in protein degradation within the endoplasmic reticulum, a process previously implicated in osteoarthritis." (PMID 35941660, 2022). "TMEM129 is a target of osteoarthritis genetic risk at this locus." (PMID 35941660, 2022). "TMEM129 is a compelling osteoarthritis susceptibility target." (PMID 35941660, 2022). "Similarly, LRIs were identified between the TSSs of TMEM129 and SLBP and an osteoarthritis-associated differentially methylated region, with functional studies confirming a regulatory role of this putative enhancer in modulating TMEM129 expression in chondrocytes." (PMID 38430365, 2024).
myelogenous leukaemia (1 paper, 2022). "Using a ChIA-PET dataset we observed an interaction between the CpGs and a region including the 5′ end of SLBP and sequence downstream of TMEM129 in K562 cells, an immortalised myelogenous leukaemia cell line." (PMID 35941660, 2022).
Wolf-Hirschhorn syndrome (1 paper, 2023). Wolf-Hirschhorn syndrome (WHS) is a developmental disorder characterized by typical craniofacial features, prenatal and postnatal growth impairment, intellectual disability, severe delayed psychomotor development, seizures, and hypotonia. "TMEM129 mutations can lead to facial dysmorphias such as Wolf-Hirschhorn syndrome and has been suggested to be a genetic risk factor for OA through disrupted protein degradation in the endoplasmic reticulum." (PMID 37619450, 2023).
tumor (1 paper, 2021). "As indicated by UALCAN database, the mRNA expression levels of HLA-A, TMEM129, UBE2D1, UBE2N, UBE2T in BCa tissue were significantly increased compared with that in normal tissue; however, the mRNA expression level of USP5 was similar between normal and tumor tissue." (PMID 34776794, 2021).
TMEM129 also shares sentences with these, for which no sentence is quoted: cancer (1 paper); glioblastoma (1); renal carcinoma (1); type 1 diabetes (1); type 2 diabetes (1).